SPATA6L (spermatogenesis associated 6 like)
Synonyms: C9orf68; FLJ10058; bA6J24.2
Tractability: No criterion of Open Targets' tractability assessment is met for any kind of drug.
Gene: Protein-coding gene on chromosome 9 (4,553,386 to 4,666,674, reverse strand). Ensembl gene ENSG00000106686.
Gene Ontology:
Molecular function: myosin light chain binding
Biological process: spermatogenesis
Cellular component: sperm head-tail coupling apparatus
Genetic constraint (gnomAD): Loss-of-function variants: 47 observed, 33.93 expected, observed/expected ratio (o/e) 1.39, 90% interval 1.1 to 1.76. The upper end of that interval is the gene's LOEUF score, 1.76, which puts it in group 6 of 6, group 1 being the genes least tolerant of losing a copy. Missense variants: 491 observed, 360.26 expected, observed/expected ratio (o/e) 1.36, 90% interval 1.26 to 1.47. Synonymous variants: 151 observed, 136.21 expected, observed/expected ratio (o/e) 1.11, 90% interval 0.97 to 1.27.
Homologues: Orthologues: chimpanzee SPATA6L (99% identical), macaque SPATA6L (94% identical), pig SPATA6L (79% identical), dog SPATA6L (77% identical), rabbit SPATA6L (75% identical), guinea pig SPATA6L (67% identical), mouse Spata6l (62% identical), rat Spata6l (61% identical), zebrafish spata6l (26% identical), Drosophila melanogaster CG14079 (15% identical). Paralogues in human: SPATA6 (31% identical).